BAP1 (BRCA1 associated deubiquitinase 1)
Diseases named in the same sentence as BAP1 in open-access papers (continued):
Sharing a sentence is not in itself a finding about the gene and the disease.
tumor (continued). "Taken together, this highlights BAP1's complex role as a tumour suppressor, whereby its high frequency of loss strongly implicates its involvement in driving PM onset, while in the mesothelial context inhibits anchorage‐independent growth and sensitises tumour cells to therapeutic intervention." (PMID 36740402, 2023). "Similarly, whilst the non-coding (deep intronic) BAP1 variant was identified in a family with a history of BAP1-related tumours, the second non-coding APC promoter variant was identified in an index case with a phenotype not consistent with the typical presentation, as previously reported." (PMID 37723522, 2023). "Finally, two important educational values should be acquired from this case: genetic predisposition and BAP1 tumor suppressor gene mutation might affect the age of presentation and overall prognosis of the disease." (PMID 35360426, 2022). "However, the complete tumor spectrum associated with germline BAP1 mutations is still uncertain." (PMID 35320498, 2022). "Consequently, BAP1 loss may promote metastasis at least in part by allowing tumor cells to evade the patient’s immune response." (PMID 35954340, 2022). "However, the role of the BAP1-deficient tumor competing endogenous RNA (ceRNA) network involved in ccRCC remains unclear." (PMID 35425712, 2022). "For instance, BAP1 mutations confer aggressive traits to renal tumors, which may increase the likelihood of renal vein invasion as well as promote de-differentiation and increased proliferation, both of which can account for a poorly visualized tumor margin." (PMID 35159060, 2022). "Moreover, some uveal melanoma tumours possess a mutation in the BAP1 gene, which is a tumour suppressor involved in the epigenetic modulation of chromatin and may suppress immune responses." (PMID 36077754, 2022). "In ccRCC, BAP1 is a key tumor suppressor gene that is involved in some important biological process including DNA repair and transcription in the nucleus, and regulating cell death and mitochondrial metabolism in the cytoplasm, and promotes tumor development when mutated in somatic cells." (PMID 36478716, 2022). "Understanding the mechanisms by which BAP1 regulates trophoblast differentiation and invasion will be important not only to uncover new molecular pathways involved in placental development, but also to shed light into the signalling pathways altered in tumours where BAP1 is mutated." (PMID 34170818, 2021). "Additionally, by analyzing the infiltration of immune cells in different immune score cohorts and whole sample groups, we found that BAP1 mutation might regulate the immune response in tumor tissues by affecting Treg cells." (PMID 34733850, 2021). "However, it should be emphasized that if the threshold for classification is adjusted according to the region analyzed, e.g., a higher threshold for classifying a tumor as BAP-1 positive (with a low risk for metastasis) in hot spots, the intratumor heterogeneity is of no prognostic significance." (PMID 33800007, 2021). "The presence of tumour-associated macrophages (TAMs) has been associated with loss of one chromosome 3 (M3, monosomy 3) and gain of chromosome 8q, while both TAMs as well as tumour-infiltrating lymphocytes (TILs) are increased in UM with loss of chromosome 3/BAP1." (PMID 34439175, 2021). "Addressing these questions is particularly important in the light of the essential role that BAP1 plays as a tumor suppressor and could provide important new insight into how BAP1 dysfunction causes cellular transformation." (PMID 33888563, 2021).
tumor (continued). "In addition, two D3 tumours carried BAP1 mutations, indicating that although BAP1 inactivation typically occurs after M38, BAP1 aberration can also occur in D3 tumours, which may or may not later undergo loss of chromosome 3." (PMID 32415113, 2020). "In addition, loss of BAP1 correlates with tumor aggressiveness and decreased time to progression." (PMID 31970090, 2019). "However, the tumor-associated functions of BAP1 may be more complex than previously thought as some studies suggest a cancer-promoting role." (PMID 31903168, 2019). "Thus, the loss of BAP1 increases ubiquitinated expression and it may sensitize tumor cells to HDAC (histone deacetylase) inhibitors, like valproic acid, trichostatin A, LBH-589, and syberynalide hydroxamic acid." (PMID 31330784, 2019). "Thus it is important to determine whether a tumor carries a BAP1 mutation, and if positive, to also evaluate a matched blood sample to establish whether the mutation is germline or somatic." (PMID 30477459, 2018). "A recently published study has shown that the heterozygous germline BAP1 mutations (BAP1+/−) induce cell metabolic changes linked to the increase aerobic glycolysis, leading to reprogramming of the activities that create a favorable environment to carcinogenesis and tumor growth." (PMID 29666782, 2018). "Additionally, in vivo evidence in nude mice has shown that injection of NCI-H226 (BAP1 negative) cells confers less tumorigenicity when these cells are infected with lentivirus carrying wild-type BAP1 compared to the mutated BAP1, further indicating its role in tumour suppression." (PMID 29085180, 2017). "In addition to providing a representative case, here we also provide a synopsis of the current understanding of these neoplasms, both in terms of the histopathological features, as well as the molecular mechanisms underlying BAP1 function and its ability to prevent tumorigenesis." (PMID 29166932, 2017). "We, therefore, hypothesize that BAP1 may have a similar function as UCHL1 and that loss of BAP1 alleviates the suppression pathways leading to activation of NF-κB, resulting in the production of cytokines and chemokines that attract tumor-specific T cells into UM." (PMID 28391358, 2017). "Interestingly, mutations in PBRM1 and BAP1 were largely observed to occur exclusively, suggesting that simultaneous loss may be disadvantageous to the tumour." (PMID 23016578, 2012). "It supports expanding the tumour spectrum of BAP1-TPDS to splenic hamartoma and possibly other benign splenic tumours." (PMID 41712014, 2026). "Although emerging studies are beginning to provide insight, evidence suggests roles for PBRM1, SETD2, and BAP1 in metabolic regulation and in shaping the tumor immune microenvironment in ccRCC." (PMID 41602827, 2026). "Recent translational work has highlighted the relevance of the tumor microenvironment and recurrent genomic alterations such as BAP1, NF2, and CDKN2A in shaping immune activity and potentially modulating response to immune checkpoint inhibitors." (PMID 41744857, 2026). "Activation of this pathway was sufficient to limit tumor growth of cell line-derived xenografts from BAP1-inactivated Ren-02 cells." (PMID 41602827, 2026). "BRCA1-associated protein 1 (BAP1), a tumor suppressor gene frequently mutated in CCA, encodes a nuclear deubiquitinating enzyme involved in chromatin remodeling and cell death regulation." (PMID 41797921, 2026). "Initially identified for its role in BRCA1 regulation, BAP1 is now known as an independent tumor suppressor involved in DNA damage repair, cell cycle regulation, and cell growth." (PMID 41551629, 2026). "BAP1 serves as a crucial tumor suppressor in ccRCC, functioning through chromatin control and the DNA damage response, particularly in homologous recombination repair." (PMID 41440218, 2025).
tumor (continued). "BAP1 has been reported to be a tumor suppressor in many cancers, for instance, uveal melanoma and mesothelioma, while conversely it has been reported to promote cell proliferation in esophageal carcinoma." (PMID 39984455, 2025). "A conventional background naevus flanking the BAP1 inactivated proliferation on one or both sides was present in majority of the tumours (n = 50, 76.9%)." (PMID 39268598, 2025). "In colorectal cancer models, tumor-endothelial interactions via adhesion molecules facilitate liver metastasis; a similar mechanism may contribute to liver tropism in UM, particularly in the context of BAP1-deficient tumors exhibiting elevated adhesion molecule expression." (PMID 41160198, 2025). "Given that EZH2 is a key component of PRC2, targeting EZH2 has been proposed as a means to disrupt the cooperative action of PRC1 and PRC2, potentially restoring the tumor‐suppressive function of BAP1." (PMID 40904706, 2025). "Comparative analysis of BAP1 expression between normal pancreatic ductal epithelial cells and tumor cells revealed a significant downregulation of BAP1 expression in the latter." (PMID 40083694, 2025). "The tumor-suppressor activity of BAP1 is partly mediated by ferroptosis through deubiquitination of H2A on the SLC7A11 promoter, resulting in repression of SLC7A11 expression." (PMID 40109379, 2025). "BAP1 is a nuclear deubiquitinating enzyme that suppresses tumor growth through its deubiquitination activity." (PMID 40904706, 2025). "A phase II trial (NCT03207347) of Niraparib in patients with BAP1 and other DDR pathway-deficient neoplasms involved 37 patients with advanced tumors." (PMID 40842586, 2025). "The high frequency of BAP1 inactivation in LMUM suggests this tumor suppressor plays a crucial role in the metastatic process." (PMID 41160198, 2025). "Tumour biomarker information was available for less than a third of the sample, with BAP1 and PD-L1 being the most common." (PMID 38970770, 2025). "Molecular alterations, including chromosomal 3p losses affecting genes such as PBRM1 and BAP1, not only contribute to angiogenesis and tumor progression but also promote an immunosuppressive tumor microenvironment (TME) that facilitates immune evasion." (PMID 40565041, 2025). "We found that BAP1 was upregulated at mRNA level in human HCCs and significantly correlated with a more aggressive tumour behaviour." (PMID 39984455, 2025). "Still, additional mutations in BAP1, SF3B1 and EIF1AX were detected in 15/17 samples and chromosome 3p and 8q copy numbers matched the primary tumour in 19/21 and 18/20 samples, respectively." (PMID 40240901, 2025). "Antigens are presented on the cell membrane of tumor cells through HLA class I. In CM cell lines, HLA class I was reported to be positively regulated by BAP1 through histone modifications." (PMID 39918475, 2025). "Specifically, AMPKα phosphorylates BAP1 at residues S123, S469, and S583, enhancing the interaction between BAP1 and pVHL and promoting pVHL stabilization and tumor-suppressive function both in vitro and in vivo." (PMID 41015595, 2025).
tumor (continued). "Surprisingly, depletion of BAP1 significantly accelerated tumor growth in BALB/c mice and shortened the animal survival rate." (PMID 39817454, 2025). "BAP1’s ability to maintain genomic integrity and regulate protein stability strongly supports its role as a tumor suppressor and highlights its important role in PCa biology." (PMID 40136571, 2025). "BAP1 is a tumor suppressor and epigenetic modifier that is frequently mutated in cancer, leading to increased aggressiveness and metastasis, as well as poor patient survival." (PMID 40754831, 2025). "Previous studies also investigated that BAP1 links ferroptosis to tumor suppression by repressing SLC7A11 expression through BAP1-mediated H2Aub deubiquitination on SLC7A11 in PDAC cells." (PMID 40083694, 2025). "Using an ex vivo liver slice model, we found that disrupting lipid metabolism with atorvastatin, an HMG‐CoA reductase inhibitor, reduced tumor burden of BAP1‐mutant UM." (PMID 40300851, 2025). "Two cases showed intermingling of the banal, smaller naevus cells with the large, epithelioid BAP1‐inactivated tumour cells, whereas most tumours had a clear demarcation of conventional naevus and BAP1‐inactivated cells." (PMID 39268598, 2025). "BAP1 alterations have a profound effect on PM biology, interacting with multiple genes and epigenetic mechanisms to develop the tumor." (PMID 40361508, 2025). "It is important to note that the CHEK2 variant data of MUM were analyzed from tumor tissue sections, and pathogenic somatic mutations in GNA11 or GNAQ, along with BAP1, were detected alongside the CHEK2 variants in the UM metastatic tissues." (PMID 40283643, 2025). "BAP1, a 3p tumor suppressor, correlates with high-grade and sarcomatoid or rhabdoid morphology, while PBRM1 and BAP1 mutations are largely mutually exclusive, BAP1-mutant tumors tending toward greater aggressiveness." (PMID 41426798, 2025). "Emerging studies have revealed both the oncogenic and tumor-suppressive function of BAP1 in mammalian cells." (PMID 39817454, 2025). "The tumor-suppressive function of BAP1 has been further supported by antagonizing the activity of the ERK1/2 signaling pathway with the U0126 inhibitor, which reduced iCCA cell proliferation, cell cycle progression, and invasion." (PMID 40723336, 2025). "Based on the known mutational status of the respective primary tumours, EIF1AX mutations were successfully identified in 6/6 vitreous fluid samples, SF3B1 mutations in 6/8 samples and BAP1 mutations in 5/5 samples." (PMID 40240901, 2025). "Most patients with RCC have a deletion of chromosome 3p and genomic alterations in the Von Hippel–Lindau (VHL) tumor suppressor allele, accompanied by the subsequent loss of other tumor suppressor genes, including PBRM1, SETD2, BAP1, and/or KDM5C." (PMID 41440218, 2025). "This will enable us to further understand the role of caly in development and prioritize contexts for further study to elucidate the role of BAP1 as a tumor suppressor in human cancer." (PMID 41022584, 2025). "With clinicopathological analysis, the upregulation of BAP1 mRNA expression was correlated with more aggressive tumor features and poorer patient overall survival." (PMID 39984455, 2025). "BAP1 is a nuclear deubiquitinase that exerts its tumor-suppressing functions by forming deubiquitinating complexes that modulate epigenetics, cell cycle regulation, DNA damage repair, metabolism, and apoptosis." (PMID 41160198, 2025). "The background naevus made up the lesser part of the tumours in all cases; the dominant component was the dermal BAP1‐inactivated proliferation." (PMID 39268598, 2025). "Compared with the adjacent non-tumor tissues, the levels of BAP1 mRNA and protein in HCC are significantly downregulated." (PMID 40607251, 2025). "Although traditionally recognized as a tumor suppressor, emerging evidence indicates oncogenic roles of BAP1 in certain malignancies." (PMID 40918144, 2025).
tumor (continued). "The interplay between TERT, p16 and BAP1 likely creates a permissive environment for tumor development by promoting immortalization (via telomere elongation), evasion of growth suppression (via p16 inhibition) and genomic instability (via BAP1 inactivation)." (PMID 39858033, 2025). "Consistent with the findings observed in the lung metastasis model, the results indicated a significant inhibition of tumor growth in the BAP1 knockout group, when compared to the control group." (PMID 40083694, 2025). "The intensity of fluorescence varied from cell to cell within the tumors, reflecting tumor cell heterogeneity in their ability to accumulate BAP-1." (PMID 41226489, 2025). "On the other hand, BAP1 also possesses tumor-suppressive functions by participating in DNA repair processes, ensuring the damaged DNA is correctly repaired before cell division." (PMID 39817454, 2025). ",41, 42, 43, 44 Observed PGVs occurred predominantly in genes related to HR and mutually exclusive with LOH in BAP1 indicating a functional impact of impaired homologous repair on tumor emergence." (PMID 40174508, 2025). "These mutations are categorized based on their timing during tumor development, with early-onset mutations (GNA11, GNAQ) and late-onset mutations (BAP1, EIF1AX, SF3B1)." (PMID 40177537, 2025). "Functionally, in the orthotopic liver injection mouse model, silencing the BAP1 predominant nuclear expression of HepG2 cells promoted intrahepatic tumor metastasis, with more frequent tumor microsatellite formation and venous invasion." (PMID 39984455, 2025). "This suggests that BAP1 acts as a tumor suppressor, though its mechanisms are still being understood." (PMID 40000790, 2025). "Chromatin remodeling gene mutations were identified in 9 of 17 tumors (53%), involving BAP1 mutations in 6 tumors (35%), SETD2 mutations in 4 tumors (24%), and an ARID1A mutation in 1 tumor (6%)." (PMID 40940841, 2025). "In a mouse model study, BAP loss resulted in an increase in EZH2 and PCR2, and BAP1 loss cells were sensitive to EZH2 inhibition, providing evidence for the potential role of BAP1 in mediating tumor sensitivity of EZH2 inhibition." (PMID 40361508, 2025). "Collectively, these findings elucidate a novel mechanism linking dysregulated glucose metabolism to compromised function of the BAP1-pVHL tumor-suppressive axis." (PMID 41015595, 2025). "Analysis of pairwise contacts in tumor samples revealed that the BAP1-low group was enriched with pan-CK–CD8+ T-cell contacts in MPM but not in MPeM cases." (PMID 38994676, 2024). "By 2022, some 234 families and 175 pathogenic or likely pathogenic germline BAP1 variants have been reported and the inclusion of other less frequent tumors in the BAP1-TPDS tumor phenotype is being discussed." (PMID 37956408, 2024). "One patient (25%) exhibited a partial response (this tumor harbored a GNA11 R183C and a BAP1 R385* mutation)." (PMID 38903495, 2024). "The tumor inhibitor BAP1 is a ubiquitin carboxyl-terminal hydrolase with deubiquitination activity that is involved in regulating many cellular processes, such as DNA damage repair and programmed cell death." (PMID 38816686, 2024). "In doing so, BAP-1 cooperates with other factors to exert inhibitory control over tumor cell proliferation activities." (PMID 39796121, 2024). "Circ_0087851 performed as a tumor suppressor and ferroptosis promoter by the miR-593-3p/BAP1 axis, providing novel biomarker and therapeutic target for the clinical management of CRC." (PMID 38642144, 2024). "In a single MM tumor from a Bap1+/+ mouse with sufficient specimen available for this analysis, there was expression of Bap1 protein but loss of detectable p16Ink4a." (PMID 38592450, 2024).